VDR (vitamin D receptor)
Diseases named in the same sentence as VDR in open-access papers (continued):
Sharing a sentence is not in itself a finding about the gene and the disease.
melanoma (continued). "Expression of the VDR has been shown to be reduced in highly pigmented melanomas and in the surrounding skin, and these tumours have a poorer prognosis." (PMID 25970336, 2015). "A similar reverse correlation between VDR expression and the aggressiveness of the tumor was reported for human melanomas." (PMID 26260259, 2015). "The antiproliferative potential of 21(OH)pD, in conjunction with its low-calcemic activity and limited requirement for genomic activity of the VDR, warrants further in vivo testing against advanced, pigmented melanomas." (PMID 25811927, 2015). "Western blotting analysis showed that the VDR is synthesized in B16-F10 mouse melanoma cells and its translocation to the nucleus is stimulated by treatment with 1,25(OH)2D3 or calcipotriol." (PMID 25811927, 2015). "In contrast to murine B16-F10 cells, treatment of human SKMEL-188 melanoma cells with 21(OH)pD resulted in partial translocation of VDR to the nucleus, suggesting possible species- or cell line-dependent differences in the response." (PMID 25811927, 2015). "In highly pigmented melanomas, the efficacy of Vitamin D analogs decreases, probably as a result of diminished VDR expression." (PMID 25811927, 2015). "VDR is present in normal skin keratinocytes and skin cancer cells derived from malignant melanomas and squamous cell carcinomas." (PMID 25887475, 2015). "The sensitivity of murine B16-F10 melanoma to Vitamin D analogs has been widely investigated with contradictory results, with the responsiveness to the treatment usually being related to VDR expression (see for review and discussion:)." (PMID 25811927, 2015). "Preclinical studies have demonstrated that several melanoma cell lines express the vitamin D receptor (VDR), and that 1,25-dihydroxy-vitamin D3 has anti-proliferative and pro-differentiation effects in cultured melanoma cells and in melanoma xenografts." (PMID 25563456, 2014). "Previously, we found that decreased expression of VDR and CYP27B1 are associated with progression of melanoma and decreased overall and disease-free survival of melanoma patients, and that novel CYP11A1-derived forms of vitamin D have anti-melanoma activity." (PMID 25334067, 2014). "Serum 25-hydroxyvitamin D3 (Vitamin D) insufficiency and single-nucleotide polymorphisms (SNPs) on its receptor, Vitamin D receptor (VDR), have been reported to be involved in melanoma susceptibility in populations mostly from northern countries." (PMID 23413917, 2013). "It has been shown that melanocytes as well as melanoma cells express VDR and that 1,25(OH)2D3 has an anti-proliferative effect on melanocytes as well as melanoma cells in vitro." (PMID 22576141, 2012). "Second, in melanoma patients, the highest nuclear VDR immunostaining was observed in melanomas with >75% of cells with p65 nuclear staining, and VDR immunostaining also correlated with the percentage of cells with nuclear NF-κB staining." (PMID 22095230, 2011). "First, we found a decrease of VDR expression in moderately and heavily pigmented melanomas in comparison with amelanotic ones." (PMID 22095230, 2011). "Cultured melanoma cells can synthesize 1,25(OH)2D3 from 25(OH)D3, express the VDR and proliferate more slowly in response to 1,25(OH)2D3." (PMID 22276021, 2009). "The vitamin D receptor has been identified in both normal melanocytes and melanoma cells." (PMID 40620564, 2025). "By analyzing 3566 primary melanoma cases, this study found that VDR SNPs may affect melanoma survival even if tumor aggressiveness was not modified." (PMID 40869905, 2025). "Similarly, VDR expression in melanoma correlates with immune score and increased patient survival, possibly because VDR signals help counteract immunosuppressive Wnt signaling." (PMID 38662827, 2024). "In addition, recent studies have indicated that the expression of VDR, RORα, and RORγ in melanomas is related to hypoxia and/or HIF1-α activity, and also affected FoxP3 expression in metastatic melanoma." (PMID 38927967, 2024).
melanoma (continued). "Overexpression of VDR in B16 melanomas lead to decreased ability to form lung metastases." (PMID 38927967, 2024). "Patients with a clinical melanoma diagnosis and ulceration who have higher VDR expression seem to have better overall survival rates compared to those who have lower VDR expression since VDR expression is usually highest in normal cells." (PMID 38672780, 2024). "Moreover, loss of keratinocytic RXRα, a dimeric partner of VDR, combined with activated CDK4 or oncogenic NRAS generated UVB-induced melanomas." (PMID 38927967, 2024). "Polymorphisms in the gene that codes for the vitamin D receptor (VDR) may also be relevant to melanoma development." (PMID 35158770, 2022). "VDR expression in skin around moles and melanoma was also significantly reduced compared to normal skin, suggesting that it may serve as a marker of tumor progression." (PMID 34206371, 2021). "Interestingly, the expression of activating vitamin D enzyme CYP27B1 was inversely correlated with melanoma progression and overall and disease-free survival times and such correlation was amplified by a concomitant decrease in the VDR expression." (PMID 34692525, 2021). "Furthermore, higher cytoplasmic VDR expression in colon and vulvar cancer, as well as in malignant melanoma, had an impact on tumor progression and prognosis." (PMID 34359656, 2021). "In addition, the secondary bile acid taurodeoxycholic acid (TDCA) can activate YAP via the vitamin D receptor (VDR) to promote melanoma metastasis." (PMID 34365464, 2021). "Thus, the expression of VDR is not only necessary for the inhibition of melanoma growth by active forms of vitamin D, but the VDR can also function as a melanoma tumor suppressor gene." (PMID 34206371, 2021). "Thus, vitamin D3 hydroxyderivatives are good candidates for melanoma therapy with their main mechanism of action involving VDR; however, action on other nuclear receptors cannot be excluded and remains to be investigated." (PMID 34206371, 2021). "Furthermore, silencing of the VDR in melanoma cells enhanced their proliferation as well as spheroid and colony formation and increased their migration rate." (PMID 34206371, 2021). "In the current study we examined the effect of knocking out the VDR on melanoma malignant behavior." (PMID 34206371, 2021). "Furthermore, spheroid formation, as an indicator of the tumor-forming ability of the cells, was more prominent in melanoma cells with the VDR knocked out." (PMID 34206371, 2021). "In this study we knocked out the VDR in a human melanoma cell line using CRISPR methodology." (PMID 34206371, 2021). "Furthermore, as revealed by analysis of transcriptome of melanoma patients, VDR expression was independently protective for melanoma-related death in both primary and metastatic disease." (PMID 35004285, 2021). "In 2009, the authors of one of the multiple meta-analyses on vitamin D and skin cancer performed a bibliographic search looking for publications that studied the relationship between melanoma, NMSC, VDR gene polymorphisms, intake of vitamin D and serum levels of 25(OH)D3." (PMID 34631325, 2021). "However, a more recent study asserts that rather than high levels of vitamin D being protective a deficiency in vitamin D (<25 nmol/L) actually shortens patient survival time from melanoma in a VDR-dependent manner." (PMID 34692525, 2021). "Activated forms of vitamin D, including classical 1,25(OH)2D3, 20(OH)D3 and 1,20(OH)2D3, inhibited cell proliferation, migration rate and the ability to form colonies and spheroids in the wild-type melanoma cell line, while VDR KO cells showed a degree of resistance to their action." (PMID 34206371, 2021). "Associations of some of the VDR genotypes with skin cancer risk have been studied, both for melanoma and non-melanoma skin cancer." (PMID 33255834, 2020).
melanoma (continued). "Recently, VDR has also been proven to exist in uveal melanocytes and melanomas as well." (PMID 32429485, 2020). "In an early study of VDR in melanoma patients, expression was found to be inversely correlated with progression from normal skin to melanocytic nevus to melanoma, suggesting a potential role in aiding differentiation between nevi and early melanoma." (PMID 32429485, 2020). "Various polymorphisms of VDR have also been found to affect the risk and prognosis of melanoma, but a consistent pattern has not been identified." (PMID 32429485, 2020). "Several polymorphisms of the vitamin D receptor (VDR) gene have a supporting effect in melanoma formation and correlate with a negative outcome in affected patients." (PMID 31717496, 2019). "Interestingly, in SK-MEL-188b melanoma cells, only one fragment of mRNA corresponding to the alternative promoter region of VDR (isoform c) was detected." (PMID 30200275, 2018). "Thus, the studies presented above on three melanoma lines are consistent with reports showing that the expression of VDR is the key factor responsible for the antitumor activities of 1,25(OH)2D3." (PMID 30200275, 2018). "It has been proposed that one of the factors influencing the responsiveness of melanoma cell lines to vitamin D3 is melanin pigmentation, which would explain the decrease in VDR expression with concomitant decrease in anti-proliferative response to 1,25(OH)2D3 in human melanoma." (PMID 30065179, 2018). "On the other hand, the expression of VDR and its splicing variants and other vitamin D related genes (RXR, PDIA3, CYP3A4, CYP2R1, CYP27B1, CYP24A1 and CYP11A1) was detected in WM98 and A375 melanomas with the transcript levels being modulated by vitamin D analogs." (PMID 30200275, 2018). "In addition, the presence of specific polymorphisms of VDR or a decreased expression of VDR, CYP27B1, CYP24A1 and defects in vitamin D signaling are linked to more advanced stages of melanoma or poorer prognosis." (PMID 30200275, 2018). "Therefore we evaluate the impact of different genotypes for phosphoinositide-3-kinase (PI3K) and vitamin D3 nuclear receptor (VDR) SNPs on melanoma patients’ outcome." (PMID 29100280, 2017). "Of note, a recent immunohistochemical study performed in human melanoma excised cells observed lower VDR protein expression in homozygous aa carries, which suggests that the aa genotype can negatively modulate tissue expression of VDR, and thus affect vitamin D actions." (PMID 28961166, 2017). "SK-MEL 188b is a spontaneous subclone of SK-MEL 188b melanoma that lacks active VDR." (PMID 26760999, 2016). "Accordingly, VDR downregulation has been observed in a proportion of melanomas and colon, breast, lung, and ovarian tumors, which may jeopardize the response to therapy with vitamin D, 1,25(OH)2D3, or its analogs." (PMID 26880977, 2016). "To establish whether the biological activity of the newly synthesized analogs of vitamin D against melanoma cells required the presence of active VDR we tested analogs for activity against the melanoma cell line SK-MEL 188b." (PMID 26760999, 2016). "To resolve whether the effect exerted by new vitamin D analogs on A375 cells is dependent on VDR, we tested analogs for activity against SK-MEL 188b human malignant melanoma cells which, as above, lack VDR." (PMID 26760999, 2016). "Furthermore, several studies demonstrated that VDR expression in melanoma cells is more intense than in normal melanocytes." (PMID 26213971, 2015). "This secosteroid could be of great value for the treatment of melanomas which display decreased expression of the VDR and enhanced expression of CYP24A1." (PMID 25811927, 2015). "Similarly, the expression of VDR is significantly higher in melanomas of less advanced, compared to more advanced, stages." (PMID 25970336, 2015).
melanoma (continued). "Considering that high frequency of polymorphisms of CYP2D6 or the polymorphism of VDR, and null for GSTM1 gene in melanoma patients, it is plausible that changes in GSTM1, CYP2D6 and VDR genes may increase the risk for both PD and melanoma." (PMID 26535116, 2015). "Finally, pigmentation of human melanomas in vivo shows a reverse correlation with the expression of VDR and CYP27B1." (PMID 25811927, 2015). "Recently, in a large case-only study, 8 VDR SNPs, 6 not previously studied, were associated with melanoma susceptibility." (PMID 23413917, 2013). "The two VDR SNPs analyzed in this study, rs7975232, and rs757343, have not been investigated for their association with melanoma yet." (PMID 22576141, 2012). "The VDR SNPs rs731236 and rs2107301 have been analyzed with respect to melanoma before." (PMID 22576141, 2012). "Except VDR rs731236 and VDR rs2107301, the other six polymorphisms have not been analyzed regarding melanoma before." (PMID 22576141, 2012). "In addition, four SNPs in the VDR gene (rs2107301, rs7975232, rs757343, and rs731236) were assessed in our 305 melanoma patients and 370 healthy controls study group." (PMID 22576141, 2012). "The melanoma samples were also assessed for VDR expression by immunohistochemistry." (PMID 22095230, 2011). "Cultured melanoma cells can synthesize calcitriol from 25(OH)D and express the VDR." (PMID 22276021, 2009). "It remains to be determined whether the anticancer effects of the vitamin D hydroxy derivatives are mediated by VDR and/or alternative receptor(s) in vivo, in addition to elucidating the mechanism of action of those novel metabolites in the melanoma microenvironment." (PMID 38927967, 2024). "In addition, pM1 melanomas were accompanied by the lower VDR in comparison to pM0." (PMID 38927967, 2024). "Similarly, for VDR, RORα and RORγ expression decreased in melanomas with active melanogenesis." (PMID 38927967, 2024). "Therefore, we propose that VDR can act as a melanoma tumor suppressor gene." (PMID 34206371, 2021). "In addition to its generalized expression, the subcellular localization of VDR to the nucleus also could be beneficial as a biomarker for melanoma progression." (PMID 34692525, 2021). "However, nuclear VDR expression in nevi versus melanoma contrasts with this." (PMID 32429485, 2020). "Thus, the decreases in both CYP27B1 and VDR expression in uveal melanomas could reflect defects in the local vitamin D signaling pattern, which could facilitate melanoma progression and invasion." (PMID 31235702, 2019). "Interestingly, sensitive melanoma lines (A375, WM98) expressed all three major VDR splicing variants, suggesting that they may play an important but not necessarily identical function in vitamin D3 signaling." (PMID 30200275, 2018). "Similarly, non-calcemic 20(OH)D3 can also activate the VDR on melanoma cells causing downstream anti-proliferative and antitumorigenic effects." (PMID 28039464, 2017). "Therefore, we compared the sensitivity of nonpigmented and pigmented melanoma cells with these forms of vitamin D. First, we have shown that treatment with vitamin D3 derivatives causes VDR translocation to the nucleus." (PMID 22095230, 2011). "An hyperactive NF-κB pathway maintains the malignant behavior of melanoma, which can be influenced by both RIPK4 and activated VDR." (PMID 40490050, 2025). "Genetic variations in VDR and the vitamin D-binding protein (VDP) genes also influence melanoma progression." (PMID 40177537, 2025). "Vitamin D3 significantly and specifically inhibited melanoma B16 cell proliferation and migration, enhanced vitamin D receptor expression, and reduced NSUN2 expression in melanoma cells." (PMID 41462962, 2025). "Additional research investigates vitamin D’s role in cancer prevention, specifically analyzing VDR, CYP27B1, CYP24A1, and ROR expression in the human uveal tract and melanoma." (PMID 40334012, 2025).
melanoma (continued). "It should be noted that the protective role of the VDR in UVR-induced skin cancers, including melanoma, connected to stimulation of anti-oxidative and DNA repair responses is widely recognized." (PMID 38927967, 2024). "Recent studies have demonstrated that 1,25(OH)2D3 through activation of VDR stimulates PTEN and inhibits AKT with a net inhibitory effect on melanoma cells." (PMID 38927967, 2024). "1,25(OH)2D3 was shown to increase caspase activity and cell viability in those human melanoma cell lines which expressed both tumor suppressors PTEN and the VDR." (PMID 38927967, 2024). "In this context, it would also be interesting to know whether expression levels of VDR and/or of other proteins involved in mediating vitamin D-induced cellular signaling, or SNPs in their corresponding genes, may have an impact on the clinical outcome in patients with advanced melanoma." (PMID 35669434, 2022). "There was a reverse correlation between melanin content and expression of the VDR and CYP27B1 as well as of RORα and γ in human melanoma samples." (PMID 34692525, 2021). "While CYP24A1 levels were high in nevi and early-stage melanomas in comparison to normal epidermis, its level decreased during melanoma progression similarly to CYP27B1 and VDR." (PMID 34692525, 2021). "Low 1α,25-dihydroxyvitamin D3 and vitamin D receptor (VDR) level correlates to increased cancer incidence and melanoma progression, respectively." (PMID 33080952, 2020). "The analysis of VDR and ROR immunostaining in the tumor cells revealed a statistically significant positive correlation between RORαn and VDRn in the melanoma cells (p = 0.030)." (PMID 31235702, 2019). "Two other melanoma lines were responsive to vitamin D (WM98 and A375) and showed relatively high expression levels of VDR transcript." (PMID 30200275, 2018). "This is reassuring from a safety point of view, but it remains of concern that in the presence of loss of expression of VDR, higher vitamin D levels might be associated with adverse outcomes for poorer prognosis melanoma patients rather than having a protective effect." (PMID 30033445, 2018). "The only report in a Spanish population found significant associations between VDR SNPs and clinical characteristics such as fair skin, absence of childhood sunburns and tumor in head-neck and trunk but not with melanoma risk, suggesting that VDR may modulate melanoma susceptibility." (PMID 23413917, 2013). "A slight decrease on VDR gene expression was observed when 5AzaCdR plus TSA treatment was given to Mel-2 and Mel-3 melanoma cells." (PMID 22984562, 2012). "An expression of the vitamin D receptor (VDR) and an anti-proliferative effect of vitamin D in melanocytes and melanoma cells have been shown in vitro." (PMID 22576141, 2012). "The active form of vitamin D3 (1,25-D3), in addition to regulating calcium and phosphate metabolism in humans through the vitamin D receptor (VDR), can inhibit the NF-κB signaling pathway and can affect the proliferation and differentiation of normal and malignant cells, including melanoma." (PMID 40490050, 2025). "Although the CPL304110 did not influence the mRNA level for VDR in A375 melanoma cells, it showed a decrease after simultaneous treatment with CPL304110 and 1,25(OH)2D3 (p < 0.01 vs. control and p < 0.05 vs. treatment with 304–110 alone)." (PMID 38473753, 2024). "Clinical data indicates that in cases of advanced melanoma, the VDR exhibits the lowest expression, whereas it is highest in normal skin." (PMID 38672780, 2024). "In RPMI7951 melanoma cells treated simultaneously with each of our tested FGFR inhibitors and 1,25(OH)2D3, but not for a monotreatment, we observed an increase in the mRNA level for VDR (p < 0.01 for CPL304110 and p < 0.01 for AZD4547)." (PMID 38473753, 2024).